IL10 (interleukin 10)
Diseases named in the same sentence as IL10 in open-access papers (continued):
Sharing a sentence is not in itself a finding about the gene and the disease.
colitis (continued). "The levels of TNF-α, IL-6, and IL-1β were increased, and that of IL-10 was decreased after DSS exposure in mice with colitis." (PMID 37047694, 2023). "Colitis caused lipid peroxidation (LP; increased MDA levels) and changes in antioxidant defense (decreased GSH levels) and inflammation profile (decreased IL-10 levels)." (PMID 37577725, 2023). "To understand the mechanisms underlying the beneficial effects of B. vulgatus and DSS-induced colitis in remote joint tissue, we assessed the expression of the anti-inflammatory cytokine IL-10." (PMID 36793721, 2023). "Reflecting the expression potential in T cells ex vivo, IL-10 serum levels contracted in DSS-colitis mice." (PMID 37275854, 2023). "Quercetin can inhibit pro-inflammatory factor generation, such as IL-17, TNF-α, or IL-6, while promoting IL-10 production during CR-induced colitis." (PMID 37111225, 2023). "Clostridium can induce the proliferation of Tregs and secrete IL-10, suppressing the inflammatory response in colitis mice." (PMID 38357144, 2023). "Consistent with previous descriptions of Il10−/− colitis in conventional mice (Keubler etal., 2015), both SM10- and SM14-colonized mice generally exhibited infiltration of Th1 and Th17 cells over time." (PMID 36993463, 2023). "G-protein-coupled receptors enhance IL-10 secretion in the antigen-specific Th1 cells of mice with colitis, thereby reducing neuroinflammation." (PMID 36981235, 2023). "We also found that IL-10 expression was induced in IL-19-treated colitis mice and prevented inflammatory infiltrates and proinflammatory cytokine expression in these mice." (PMID 37375032, 2023). "Fecal microbiotas from IBD patients and Il10−/− mice developing colitis decrease gut macrophage YTHDC1 expression in wild‐type mice." (PMID 36922750, 2023). "It has been reported that A. muciniphila secretes the Amuc_1100 protein, which induces the anti-inflammatory cytokine interleukin-10 via toll-like receptor 2 and improved colitis in mice." (PMID 37444313, 2023). "The genus Bifidobacterium is a beneficial probiotic that prevents intestinal inflammation by inducing intestinal IL-10-producing regulatory T cells and ameliorating colitis." (PMID 38004761, 2023). "Treatment with the zonulin inhibitor AT-1001 markedly diminished the severity of IL-10 knockout colitis." (PMID 36678175, 2023). "Clostridium butyricum prevents acute experimental colitis in mice by inducing IL-10 production in intestinal macrophages." (PMID 37849749, 2023). "NOD2 signaling promotes hyper-reactive macrophages and colitis in IL10-deficient mice, and NOD2 deficiency in IL10−/− mice leads to a significant improvement in chronic colitis." (PMID 36814903, 2023). "We analyzed the effect of resveratrol on mast cells in vivo in ovalbumin-induced allergic enteritis as well as experimental colitis in IL-10−/− mice which received resveratrol via drinking water." (PMID 35163137, 2022). "The evidence for an important role of microbiota in regulating immune response is provided by interleukin (IL)-10 knock out mice (Il10−/−), which develop spontaneous colitis due to microbial-induced activation of effector T cells." (PMID 35112169, 2022). "VDR favors FoxP3+ T reg cells, which prevent the development of experimental colitis through the production of inhibitory cytokines such as IL-10 and TGF-β and FoxP3+ T reg cells are induced by 1,25(OH)2D3 treatments in vitro and in vivo." (PMID 35057450, 2022). "An IL-10 dependent protective role of TCRαβ+CD8αα+ IELs was reported in the colitis of SCID mice induced by CD4+CD45RBhiTCRαβ+ thymus-derived T cells." (PMID 34999729, 2022). "Co-administration of peritoneal IL-10 competent B cells also reduced the severity of colitis induced by the intraperitoneal administration of CD25-CD45RBhi CD4 + T cells." (PMID 35672305, 2022). "Transferring IBD microbiota induces more severe colitis in IL-10−/− mice and enhances naïve CD4+ T cell-induced colitis severity in Rag1−/− mice." (PMID 36076980, 2022).
colitis (continued). "A recent study reported that TNF‐α increased macrophage expression of phosphatase Shp2, which exacerbated colitis by desensitizing macrophages to the anti‐inflammatory function of IL‐10." (PMID 35593111, 2022). "Colonic shortening as a proxy for intestinal inflammation and histological colitis scores were markedly reduced in Il10−/− mice immunized with CTB-Ent compared to CTB controls." (PMID 36094114, 2022). "This is in agreement with previous reports that showed that Il10–/– mice reared in germ-free conditions remained disease-free, and only inoculation with specific commensal bacterial strains induced colitis via an antigen-driven Th1 response." (PMID 36290283, 2022). "Meanwhile, CD69 has the ability to enhance the immunosuppressive function of Tregs and to alleviate colitis by improving IL-10 production." (PMID 35565775, 2022). "Bacteroidetes is the most abundant group in the gut, which can interact with treg cells to promote the secretion of IL-10, thereby protecting mice from pathogen-induced colitis." (PMID 35684007, 2022). "In agreement with this, polymorphisms in genes coding for the immunoregulatory cytokine IL-10 (IL10) or subunits of the IL-10 receptor (IL10RA, IL10RB) are strongly associated with human IBD, particularly with early onset forms of colitis." (PMID 35572569, 2022). "For instance, IL-10+FOXP3- splenic Tr1 cells are less protective against colitis development in contrast to their intestinal counterparts." (PMID 36389662, 2022). "Recent studies reported that DSS colitis severity is associated with increased production of various inflammatory mediators such as TNF-α, IL-1β, and MPO activity; and IL-10 and TGF-β drive anti-inflammatory response to prevent colitis." (PMID 36193153, 2022). "Three different mouse models were analysed: the colitis-associated colorectal cancer (AOM/DSS), the acute colitis (acute-DSS), and the IL-10 KO mouse models." (PMID 36266428, 2022). "Semaphorin 7A, expressed on basolateral IECs, binds to αvβ1 integrin on IMφs, thereby triggering macrophage production of IL‐10, which was shown to ameliorate colitis." (PMID 35593111, 2022). "The absence of Pygo2 attenuated the development of MAT lesions in Il‐10−/− mice by promoting the differentiation of adipocytes, leading to the amelioration of colitis partly through the Axin2/GSK3β pathway." (PMID 35707871, 2022). "Meanwhile, it significantly elevated the IL-10 level to inhibit inflammation in DSS-induced colitis." (PMID 36171753, 2022). "Taken together, these data indicate that transfer of ST4-altered gut microbiota in DSS-induced colitis recipients increases SCFAs production and induces accumulation of IL-10-producing Treg cells." (PMID 35435504, 2022). "The propionate causes Foxp3 + Tregs to produce IL-10, and through the GPR43 signaling pathway, inhibiting histone deacetylase (HDAC) activity to prevent colitis." (PMID 35844804, 2022). "In this study, JPQCD significantly improved UC symptoms, such as weight loss, increased DAI, and improved colonic shortening and colorectal bleeding in IL-10−/− mice with piroxicam-induced colitis." (PMID 35186102, 2022). "In fact, IL-10 levels were significantly lower in UCC118TM-fed mice compared to PBS control mice recovering from colitis." (PMID 35889102, 2022). "Taken together, our results revealed that intraperitoneally delivered MSCs alleviated colitis in mice, likely by boosting IL-10-producing B cells in the peritoneal cavity." (PMID 35371051, 2022). "Our data indicated that SSP inhibits the differentiation of TNF-α+ DCs and MHC-II+ DCs, and increases the secretion levels of IL-10, further rebuilding the balance of GM in colitis mice with SKYD syndromes." (PMID 36310616, 2022). "Male Il10-/- mice (8–10 weeks, n = 12/group) were irradiated with either sham, γ-rays or heavy-ions (28Si or 56Fe), and histopathological assessments for colitis and CAC were conducted at 2.5 months post-exposure." (PMID 36584137, 2022).
colitis (continued). "The administration of T. halophilus to DSS-induced colitis mice also increased the frequencies of IL-10+ cells in CD4+ T cells (36.31 ± 10.62% vs. 12.61 ± 4.45%, p < 0.05) and CD8+ T cells (38.97 ± 9.79% vs. 13.26 ± 6.74%, p < 0.05)." (PMID 35741032, 2022). "The pro-inflammatory cytokines TNF-α, IL-1β, IL-6, IL-12, and IFN-γ levels in mice with DSS-induced colitis were apparently higher than those of mice in the normal group, but anti-inflammatory cytokine IL-10 was lower (P < 0.05)." (PMID 36171753, 2022). "When the IL-10 receptor (IL-10R) gene in Treg cells in the mouse model is knocked out, it will develop into colitis under the action of Th17 cells, highlighting the indispensable role of IL-10 in maintaining the stability of the intestinal environment." (PMID 36189293, 2022). "CD4+CD8A+ T cells in the intestine expressed IL10, which is essential for the inhibition of colitis." (PMID 36353619, 2022). "Daidzein is one of the isoflavones that reduces IL6-, IL-8, IL-12, INF-γ, and up-regulates IL-10 in mesenteric lymph node cells in DSS-induced colitis." (PMID 35566252, 2022). "What is relevant in this context, milk fat promotes the onset and incidence of colitis in IL-10−/− mice, driving it from a spontaneous rate of 25–30% to over 60% in a 6-month period." (PMID 35954180, 2022). "Several novel therapeutic interventions interfering with lymphangiogenesis have been studied in DSS or IL-10 KO colitis mouse models." (PMID 35163775, 2022). "In DSS colitis model, Clostridium butyricum directly triggers TLR2/MyD88-dependent IL-10 production by intestinal macrophages in inflamed mucosa to prevent colitis development, and this prevention can be negated in macrophage-specific IL-10-deficient mice." (PMID 35967333, 2022). "H. hepaticus strongly induces cognate Ag-specific RORγt+ Foxp3- Th17 responses in IL-10-/- mice or mice treated with IL-10 blockades, thereby inducing the experimental colitis." (PMID 36310871, 2022). "We established a mouse model of chronic colitis by adding 200 ppm piroxicam feed to IL-10−/− mice for 10 d to evaluate the therapeutic effect of JPQCD." (PMID 35186102, 2022). "In a T-cell transfer colitis mouse model, asparaginyl-tRNA synthetase induced IL-10 production in splenic cells and mice treated with this protein showed resolution of cellular infiltration in their colonic mucosa and induced a CD8+ cellular response." (PMID 36032131, 2022). "Some researchers used intestinal bacterial strains isolated from mice with colitis to stimulate murine peritoneal macrophages in vitro and found that IL-10 can be secreted from macrophages induced by L. murinus." (PMID 35241180, 2022). "Due to the constitutive presence of ILCregs in the intestines and their expansion seen during dextran sodium sulfate (DSS)-induced colitis in Rag-/- mice, ILCregs have been conjectured to maintain gut tolerance through production of IL-10." (PMID 36275689, 2022). "Some studies reported that the expression of IL-10 in the colon was reduced in mice with DSS-induced colitis, and Wogonin enhanced IL-10 production by inducing transcript factor HIF-1α expression via the AKT/GSK3β signal pathway." (PMID 36176442, 2022). "It was shown that this strain increased the production of IL-10 in the intestinal epithelium, contributing to its effectiveness against colitis." (PMID 35628274, 2022). "Patients exhibited improved colitis symptoms in three trials, juxtaposed to two other trials where IL‐10 supplementation failed in alleviating colitis." (PMID 35593111, 2022). "Studies have also reported that gavage of Akkermansia led to increased severity of colitis in iL10-/- mice." (PMID 36713373, 2022). "Bacteroidetes, specifically Bacteroides fragilis, induces the production of IL-10 by stimulating Th1 and Treg cell responses and protects mice from pathogen-induced colitis." (PMID 35200626, 2022).
colitis (continued). "Lentiviral transfection was used to regulate Pygo2 expression in Il‐10−/− mice, and the effects on mesenteric adipocyte differentiation, inflammation, and dysfunction during spontaneous colitis, as well as the possible mechanism, were investigated." (PMID 35707871, 2022). "In this study, piroxicam was added to the model feed at 200 ppm for 10 d to induce colitis in IL-10−/− mice, and the mice in the model group showed significant weight loss, thin fecal matter, and positive fecal occult blood test." (PMID 35186102, 2022). "Short-term intake of high glucose or fructose does not trigger inflammatory responses in the gut of healthy mice but aggregates colitis in DSS-treated mice or IL-10−/− mice; both are known to have a leaky gut." (PMID 36076980, 2022). "Rather, as evidenced by the tendency of TLR5 knockout mice to develop colitis, flagellin contributes to negatively regulating the response to gut microbiota via IL-10 production and by stimulating regulatory CD4+ T cells." (PMID 36555214, 2022). "Recombinant Lactococcus lactis expressing murine IL-10 protected IL-10−/− mice from colitis and significantly reduced inflammation in mouse colitis induced by dextran sodium sulphate (DSS)." (PMID 35672695, 2022). "In colitis models, oral uptake of these particles decreased the pro-inflammatory cytokines (TNF-α, IL-6, and IL-1), raised the anti-inflammatory cytokines (IL-10 and IL-22), and was shown to be a preventive therapy against colitis-related malignancy." (PMID 36298592, 2022). "They further determined that cure of colitis was IL-10 dependent, and that IL-10 producing CD4+CD25+ Tregs were mainly located in the lamina propria of the intestine suggesting functional compartmentalization of CD4+CD25+ T cells during disease states." (PMID 36466912, 2022). "In the second model, the ability of LL-mIL10 to prevent disease was tested in IL-10-/- mice, a model that spontaneously develops colitis." (PMID 36104776, 2022). "To obtain more information with respect to chronic colitis, we further studied the role of CS supplementation in chronic DSS-induced colitis and IL-10-knockout colitis mice model." (PMID 35908039, 2022). "IL-10 is an anti-inflammatory cytokine reported to have elevated levels in colitis patients, and our current study has replicated these results in DSS-treated mice." (PMID 36365201, 2022). "H. hepaticus has been reported as a colonizer of the lower bowel in immunocompetent mice, driving IL-23-dependent colitis in mouse models defective in IL-10 signaling." (PMID 35572549, 2022). "In line, in the IL-10 gene-deficient IBD mouse model, increased intestinal permeability was observed early in life and then mice spontaneously developed colitis at 12 weeks age." (PMID 36233559, 2022). "We observed significantly increased epithelial damage, a reduced number of goblet cells and immune cell infiltration in all IL-10−/− groups as well as delayed onset of colitis symptoms." (PMID 35163137, 2022). "Although B. bifidum BGN4-pBESIL10 exerted anti-inflammatory effects in vitro, the enhancement of IL-10 production and alleviation of colitis were very limited." (PMID 35672695, 2022). "IL-10−/−/β7−/− mice developed worse colitis than their β7-sufficient counterparts, as indicated clinically by lower body weights, hypothermia, and decreased survival, as well as the nearly uniform development of rectal prolapse." (PMID 34433904, 2022). "As increase in MC numbers in OVA-induced allergic enteritis was prevented by resveratrol application, we further aimed to check for resveratrol effects in experimental colitis of IL-10−/− mice." (PMID 35163137, 2022). "In vivo, Foxp3-specific knockout of CREB prevents colitis in a T cell mediated transfer colitis model in an IL-10 dependent way however aggravates disease activity in a murine lupus and asthma model." (PMID 36096831, 2022).
colitis (continued). "BAFF in other models of inflammatory bowel disease such as TNBS colitis model and IL-10 knockdown colitis model and also human THP-1 cells remains to be explored further." (PMID 35320937, 2022). "Stimulation of CD4+ T cells to produce IL-10 inhibits the inflammatory response in the process of colitis." (PMID 35794311, 2022). "Some studies indicated that the increased abundance of Lachnospiraceae_UCG-006 improves the differentiation of Treg cells and restores the secretion levels of IL-10 in experimental colitis." (PMID 36310616, 2022). "The results showed that apigenin increased the level of IL-10 in the colitis of DSS-induced colitis mice (P < 0.05)." (PMID 36590200, 2022). "The role of IL-10 in IBD pathogenesis was also demonstrated using Il10−/− mice; it increased infiltration of leukocyte and macrophages with persistent colitis symptoms compare to normal-type mice." (PMID 35277165, 2022). "UCC118TM-mediated IL-10 induction was effective at delaying the onset of colitis; however, its action during the recovery phase of colitis was IL10-independent." (PMID 35889102, 2022). "Compared to chemical-induced colitis models, interleukin-10 knockout (IL-10−/−) mice are often applied in mechanistic studies to examine the pathogeny of spontaneous, immune-mediated, chronic gastrointestinal inflammation." (PMID 35662934, 2022). "It was also demonstrated that while IL-10 mutant mice develop spontaneous colitis under normal conditions, housing IL-10 mutant mice in a pathogen-free facility resulted in lesser disease severity." (PMID 35625485, 2022). "In mice treated with colitis-inducing dextran sodium sulfate (DSS) there was some indication that Bt BEVs improved survival, weight loss, disease activity and increased IL-10 production." (PMID 36439842, 2022). "Activating the Hedgehog signal pathway inhibits the development of colitis by up-regulating the expression of anti-inflammatory cytokine IL-10 while inhibiting the Hedgehog signal pathway lead to inflammatory bowel disease." (PMID 35690747, 2022). "According to one study, in a mouse model of IL-10 gene-deficient colitis, H. hepaticus induced inflammatory Th17, increased IL-17A and IFN-γ expression, and aided in the development of colitis." (PMID 36590401, 2022). "El-Mahdy and his workmates reported that mesalazine can enhance anti-inflammatory effects to attenuate progression of oxazolone-induced colitis by restoring IL-10 and ZO-1 levels and limiting IL-6/STAT-3 trans-signaling." (PMID 35388299, 2022). "On the other hand, butyrate administrated 2 weeks prior to DSS-induced colitis (group 4) tended to increase the plasmatic level of anti-inflammatory cytokine IL-10 compared to the DSS group." (PMID 35928257, 2022). "Treatment with β-glucans increased the production of IL-10 mediated by PPARγ, promoting the attenuation of colitis and elimination of C. glabrata." (PMID 35630457, 2022). "Collectively, our study revealed that intraperitoneally delivered MSCs secreted THBS1 to boost IL-10+Bregs and control the progression and recurrence of colitis, providing new insight for the prevention and treatment of IBD." (PMID 35371051, 2022). "Other previous studies implied that recombinant L. lactis and B. bifidum expressing IL-10 exerted mildly anti-inflammatory effects on DSS-induced colitis, but only for some clinical parameters, which are consistent with our in vivo study." (PMID 35672695, 2022). "Recent animal studies showed that the perivascular sensory neurotransmitter function of mesenteric arteries is significantly impaired in an IL-10 knockout mouse colitis model." (PMID 36009796, 2022). "In one of the study, gingivae-derived MSCs was able to reduce both clinical and histopathological severity of colonic inflammation and was able to reduce the inflammatory infiltration of T cells and expression of anti-inflammatory cytokine like IL-10." (PMID 35782071, 2022).